LINC00607 (long independently transcribed non-coding RNA 607)
Gene: Long non-coding RNA gene on chromosome 2 (215,611,563 to 215,925,887, reverse strand). Ensembl gene ENSG00000235770.
Diseases named in the same sentence as LINC00607 in open-access papers:
LINC00607 is named in the same sentence as 10 diseases in open-access papers, as found by Europe PMC text mining. Sharing a sentence is not in itself a finding about the gene and the disease. The quoted sentences say what the papers report.
atherosclerosis (2 papers, 2023 to 2026). A disease characterized by the build-up of fatty material and calcium deposition in the arterial wall resulting in partial or complete occlusion of the arterial lumen. "Furthermore, the corresponding orthologue of LINC00607 was strongly induced in Macaca fascicularis samples undergoing atherosclerosis regression after a high fat diet." (PMID 36700983, 2023). "Key eRNAs, including IRENES, CARMEN, LINC00607, HERNA1, PSMB8-AS1, and WISPER, are discussed in detail, emphasizing their roles in pathological processes, such as cardiac development, vascular remodeling, atherosclerosis, and fibrosis." (PMID 40491378, 2026).
endothelial dysfunction (2 papers, 2020 to 2024). In vascular diseases, endothelial dysfunction is a systemic pathological state of the endothelium (the inner lining of blood vessels) and can be broadly defined as an imbalance between vasodilating and vasoconstricting substances produced by (or acting on) the endothelium. "It has been recently established that LINC00607 (“607”) is an important regulator and mediator of endothelial dysfunction." (PMID 38247509, 2024). "Collectively, these data support that perturbing the RNA–chromatin contacts, exemplified by LINC00607 knockdown, led to the suppression of SERPINE1 and endothelial dysfunction." (PMID 33060583, 2020). "Notably, the Ri pre-treatment of HUVECs also suppressed the expression of ENOS, LINC00607, and TSP1 and prevented MG adduct-induced endothelial dysfunction, evaluated by endothelial homeostasis via eNOS and vascular permeability." (PMID 38247509, 2024).
lung adenocarcinoma (2 papers, 2022 to 2023). A carcinoma that arises from the lung and is characterized by the presence of malignant glandular epithelial cells. "Furthermore, LINC00607 was described to be required for tumor proliferation of osteosarcoma cells and was downregulated in lung adenocarcinoma." (PMID 36700983, 2023).
osteosarcoma (2 papers, 2023). A usually aggressive malignant bone-forming mesenchymal neoplasm, predominantly affecting adolescents and young adults. "For example, LINC00607 is upregulated in osteosarcoma and its knockdown suppresses osteosarcoma cell growth, invasion, and migration via completely binding to miR-607 and downregulating E2F transcription factor 6 expression." (PMID 37333453, 2023).
diabetes (1 paper, 2022). "Together, our findings highlight LINC00607 as an emerging crucial epigenetic regulator in the vessel wall and the potential of targeting SE-derived lncRNAs such as LINC00607 for improved treatment or reversal of CVDs and metabolic memory in diabetes-associated vascular complications." (PMID 35837599, 2022). "Along these lines, we previously found that inhibition of LINC00607 in diabetes-mimicking HT condition significantly suppressed endothelial inflammatory response as evidenced by suppression of monocyte adhesion to ECs." (PMID 35837599, 2022).
tumor (3 papers, 2020 to 2023). "Since approximately 25% of OS patients have pulmonary metastasis when diagnosed, and since EMT is important for the metastatic dissemination of tumor cells, we investigated whether any change in the expression of LINC00607 affected EMT." (PMID 33585204, 2020). "We injected pCDH-LINC00607 and pLKO-1-LINC00607 OS cells into the flanks of female WT nude mice to establish a subcutaneous tumor model to further investigate if LINC00607 could affect tumor growth in vivo." (PMID 33585204, 2020). "This indicated that LINC00607 affected in vivo OS tumor growth directly." (PMID 33585204, 2020). "Further, we identified that LINC00607 acted as an miR-607 sponge to modulate E2F6 expression and directly regulated the in vivo tumor growth of OS." (PMID 33585204, 2020). "In this study, we innovatively illustrated that LINC00607 was markedly downregulated in NSCLC, and LINC00607 suppressed NSCLC cell growth, migration, and invasion via modulating the miR-1289/EFNA5 axis, which indicated that LINC00607 functioned as a tumor suppressor in NSCLC." (PMID 37333453, 2023).
cardiovascular diseases (1 paper, 2023). "The function of LINC00607 in cardiovascular diseases with hypoxia signaling needs more investigation as LINC00607 might be a potential therapeutic target or clinical marker." (PMID 36700983, 2023). "Importantly, LINC00607 expression was altered in various cardiovascular diseases." (PMID 36700983, 2023). "Taken together, these findings suggest that LINC00607 is involved in securing endothelial BRG1 and ERG-dependent target gene expression, as well as appropriate responses to stress and cardiovascular diseases." (PMID 36700983, 2023).
LINC00607 also shares sentences with these, for which no sentence is quoted: thyroid cancer (2 papers); cancer (1); non-small cell lung carcinoma (1).